INS (insulin)
Diseases named in the same sentence as INS in open-access papers (continued):
Sharing a sentence is not in itself a finding about the gene and the disease.
Hypoglycemia (continued). "Also necessary are daily care measures such as carbohydrate counting, multiple daily insulin doses (MDI) or use of an insulin pump, capillary blood glucose monitoring, or use of blood glucose sensors for management of hyper- and hypoglycemia." (PMID 36219199, 2022). "Although information on the frequency or severity of hypoglycemia after treatment change is lacking, Dulaglutide may improve compliance by reducing unfavorable hypoglycemia, compared to insulin." (PMID 35784534, 2022). "Moreover, insulin intensification, such as that by a multiple daily injection regimen, frequently increases the risks of adverse events such as weight gain and hypoglycemia." (PMID 35784534, 2022). "Our study has shown a better HRQoL in patients coming from the secondary public service, which can be attributed to the higher number of patients using insulin analogs and presenting less hypoglycemia, which are important factors affecting the HRQoL of our patients." (PMID 35773385, 2022). "Hypoglycemia (<54 mg/dl or severe) was reported in five (1%), four (1%), and eight (2%) participants on tirzepatide 5, 10, and 15 mg, respectively, versus 26 (7%) on insulin degludec." (PMID 36313764, 2022). "Octreotide, a long-acting analog of somatostatin, inhibits insulin release and may control hypoglycemia in patients in whom diazoxide has failed." (PMID 35296370, 2022). "Thus, getting borderline results of insulin and C-peptide during the background of hypoglycemia should be interpreted very carefully." (PMID 36376919, 2022). "Importantly, the use of insulin has some disadvantages, among which is the need to closely monitor the patient’s glucose levels to avoid hypoglycemia." (PMID 36060943, 2022). "The estimated effect of metformin showed improvements in birth weight than insulin (WMD – 102.58 g, 95% CI −180.45 to −25.49) and glyburide (WMD – 137.84 g, 95% CI −255.31 to −25.45), for hypoglycemia within 1 h of birth than insulin (OR 0.65, 95% CI 0.47 to 0.84)." (PMID 36530712, 2022). "Moreover, a hospital-wide, nurse-driven hypoglycemia protocol can also be default-selected when ordering insulin using the order set." (PMID 35917098, 2022). "If amylin was provided along with insulin, which then caused a hypoglycemic state, then gastric emptying was accelerated at a similar rate as when insulin induced hypoglycemia in the absence of amylin." (PMID 35456307, 2022). "In addition to T2D, the model developed was also used to explore the role of hysteresis in insulin secretion in explaining phenomena such as post prandial glucose lowering and a related pathophysiology reactive hypoglycemia." (PMID 36148302, 2022). "To facilitate the post-mortem investigation in cases of suspected death due to insulin or OHA overdose or death from suspected hypoglycemia, we provide a flowchart that could help forensic pathologists." (PMID 36359343, 2022). "However, while never reported in cats, xylitol ingestion in dogs stimulates insulin secretion resulting in potentially lethal hypoglycaemia." (PMID 35968003, 2022). "Patients using sulfonylurea derivates or insulin are more prone to this latter complication and may also develop hypoglycaemia." (PMID 34097240, 2022). "On the other hand, hypoglycemia induced by insulin infusion in non-diabetic male subjects was associated with a rise in pro-inflammatory cytokines, markers of lipid peroxidation by thiobarbituric acid assay, and reactive oxygen species." (PMID 36011166, 2022). "Thus, it appears that endogenous opioids are primarily released when there is an increased need for available glucose, such as during insulin-induced hypoglycaemia or during exercise, which is in line with the hyperglycaemic effects of opioid stimulation." (PMID 35593927, 2022).
Hypoglycemia (continued). "This correlation between clinical inertia and insulin therapy can be, at least partially, explained by the fear of hypoglycemia, weight gain, injections, influence on patients’ everyday life, and treatment complexity, which was pointed out in other papers researching this phenomenon." (PMID 35457303, 2022). "The effects of different insulin subtypes and dosing strategies on hypoglycemia." (PMID 35634376, 2022). "This investigation aims to differentiate insulin intoxication deaths by metabolomics, and identify a metabolic fingerprint to screen for unknown hypoglycemia-related deaths." (PMID 36676928, 2022). "The hepatic suppression of FOXO1 and FOXO3 causes hypoglycemia and hyperlipidemia in FOXO1 and FOXO3 knockout mice; moreover, the expression of hepatic FOXOs affects the reduction of gluconeogenic gene expression and insulin resistance." (PMID 35256743, 2022). "Between two RCTs and one cohort study, rapid-acting insulin analogs significantly improved post-iftar blood glucose and overall blood glucose compared to regular human insulin without the risk of increased hypoglycemia." (PMID 35634376, 2022). "Within a one-year follow-up period of insulin initiation, the rate of hypoglycemia was 13.1%." (PMID 36149907, 2022). "These include insulin checks, possibly evaluating ketone levels, verifying recent episodes of hypoglycemia, carbohydrate intake before and after exercise and monitoring for post-exercise hypoglycemia depending on professional scope of practice." (PMID 35360229, 2022). "The first conclusion of these comparisons introduced in section 3.3 is that safety features to prevent hypoglycaemia are necessary (an Insulin-On-Board (IOB) limitation in the control algorithm is implemented in both cases), even when meal announcement lessen the constraint on the controller." (PMID 35528003, 2022). "Studies reported insulin-induced hypoglycaemia could lead to migraine-like pain since blood glucose levels dropped suddenly." (PMID 35627115, 2022). "However, in the presented case insulin, C-peptide and proinsulin were all low in the presence of hypoglycemia, suggesting hypoinsulinemic hypoglycemia and seemingly excluding surreptitious insulin administration." (PMID 36376919, 2022). "We initially suspected that increased production of insulin or a failure to produce glucagon might be the basis of hypoglycemia." (PMID 36548717, 2022). "This study aimed to determine whether Super Bolus is more effective than Normal Bolus in preventing PPH and avoiding late hypoglycemia after an h-GI meal in children with T1D treated with continuous subcutaneous insulin infusion." (PMID 35351180, 2022). "When adjusting to HbA1c of 53 mmol/mol (7%), an internationally recognized target for glycemic control, estimated minutes in hypoglycemia (per week) were 137.2 (95% CI 49.6 to 224.7), 290.9 (168.8 to 413.0) and 751.9 (433.9 to 1070.0) with metformin, SU and insulin, respectively." (PMID 35450869, 2022). "Therefore, human islet transplantation fostered the protection from SHEs in subjects who had earlier shown significant episodes of intractable impaired awareness of hypoglycemia and SHEs even after insulin treatment." (PMID 36686451, 2022). "PPAR panagonists have also been confirmed to significantly reduce abnormally elevated blood glucose levels without causing hypoglycaemia, improve insulin resistance, and moderate impairment of insulin secretion." (PMID 35547000, 2022). "In addition, studies have suggested that a lower glycemic variability (CV) target of <33% provides additional protection against hypoglycemia for those receiving insulin or sulfonylureas." (PMID 35170854, 2022). "However, frequency of clinical hypoglycemia was recorded more among patients treated with premixed insulin-based regimen than patients treated by NPH insulin-based therapy." (PMID 35617250, 2022).
Hypoglycemia (continued). "In addition, laboratory indicators were also suspicious of factitious hypoglycemia due to the introduction of insulin analogues, so it was decided to conduct an additional study of insulin with the Abbot kit." (PMID 36376919, 2022). "In spite of the absence of other risk factors, patients receiving intensive insulin therapy are more likely to experience hypoglycemia." (PMID 36318542, 2022). "The insulin release indexes were 0.55 and 0.52 (normal range < 0.3) when the hypoglycemia occurred." (PMID 35255927, 2022). "We hypothesized that hypoglycemia was mainly related to exogenous insulin administration and their impaired response to oral supplementation." (PMID 35813646, 2022). "In our study, participants’ CGMs were blinded which could explain why only two participants applied insulin basal rate reduction to prevent hypoglycemia." (PMID 36237197, 2022). "Hypoglycemia is a common complication of insulin treatment in hyperkalemic patients." (PMID 36371171, 2022). "It is presumed that elevated insulin may be responsible for normoglycemia or even relative hypoglycemia in SZ patients at an early stage of their first-episode." (PMID 36620683, 2022). "The mechanisms by which insulin-induced hypoglycemia causes sudden death are not well characterized." (PMID 35406129, 2022). "Hypoglycemia is a common complication in diabetic patients receiving oral or insulin therapy." (PMID 35858952, 2022). "This wide range may be due to differences in the definitions for hypoglycaemia, differences in the study populations and the insulin/dextrose regimens." (PMID 35552566, 2022). "But it is still unknown how serotonergic system is activated in response to insulin-induced hypoglycemia." (PMID 35910256, 2022). "Adverse effects from high doses of insulin include weight gain and excessive hypoglycemia." (PMID 35502441, 2022). "However, the odds of any hypoglycemia (OR=8.19, CI=5.60-11.98) and symptomatic hypoglycemia (OR=6.15, CI=1.88-20.15) were significantly higher in patients receiving intravenous insulin therapy." (PMID 36589857, 2022). "Prolonged hypoglycaemia reduced c-peptide levels, islet volume and almost depleted islet insulin." (PMID 35982111, 2022). "If the patient had a repeated dose of insulin or glucose (during the period of assessment the endpoint as the posttreatment hypoglycemia), only the lowest blood glucose before being given the repeated dose would be determined as the posttreatment blood glucose level." (PMID 36371171, 2022). "Thus, the presence of artificial hypoglycemia due to exogenous administration of insulin analog preparation, i.e. the diagnosis of Munchausen syndrome, was confirmed." (PMID 36376919, 2022). "However, the brain, particularly the VMH, is initially involved in CRR to insulin-induced hypoglycemia." (PMID 35619170, 2022). "As our own screen was based on insulin-induced hypoglycemia Agpat5 could, in principle, mediate its effect on glucagon secretion by controlling insulin sensitivity and hypoglycemia development and/or on hypoglycemia sensing." (PMID 36180454, 2022). "An insulin-to-glucose ratio > 0.3 at the onset of hypoglycemia may provide a basis for diagnosing insulinoma." (PMID 35916979, 2022). "Studies about the safety and efficacy of metformin in GDM show that metformin is associated with a lower risk of gestational hypertension, pre-eclampsia, macrosomia, and neonatal hypoglycemia compared with insulin therapy, even though the glycemic control profiles are found to be comparable." (PMID 35745174, 2022). "In the present rat model, chronic gestational insulin-induced hypoglycaemia has been shown to lead to delayed development and decreased growth of foetuses, as well as decreased foetal/placental weight ratio at end of gestation, resembling an intra-uterine growth restricted foetal phenotype." (PMID 35344549, 2022).
Hypoglycemia (continued). "The daily insulin may have a slightly protective effect on the development of hypoglycemia, which was comparable between the two treatment regimens in our study." (PMID 36091534, 2022). "The decreased incidence of hypoglycemia reported in the studies, which most likely happens because dapagliflozin operates independently of the glucose dependent production of insulin by the pancreatic beta cells, was another therapeutic benefit of dapagliflozin." (PMID 36457541, 2022). "At the time of hypoglycemia, suppressed serum insulin, GH and IGF-1 levels was found." (PMID 36211262, 2022). "This suggests the possibility that hypoglycemia resulted from the overproduction of insulin." (PMID 36548717, 2022). "Furthermore, in cluster C6 we identified a moderate presence rate of the ATC code ‘H04AA’, which is a glucose-lowering drug mainly indicated to treat severe hypoglycemia reactions in diabetics treated with insulin." (PMID 36064616, 2022). "In addition, the results of insulin tolerance tests showed that chronic intraperitoneal injection of GnIH significantly weakened insulin-induced hypoglycemia after insulin challenge over 120 min." (PMID 35897643, 2022). "Insulin therapy is expensive, and hypoglycemia is a significant component of economic evaluation." (PMID 35343912, 2022). "Acute and recurrent hypoglycemia were then induced by glucose via insulin administration." (PMID 35915611, 2022). "Currently, novel hypoglycemic drugs exhibit the unique, ideal property of promoting insulin secretion in a glucose-dependent manner without causing hypoglycemia." (PMID 36204104, 2022). "We used multiple insulin boluse injections to decrease the blood glucose levels to hypoglycemia." (PMID 36050392, 2022). "LGS technology was further refined in the form of predictive low-glucose suspend (PLGS) systems, which contain algorithms that predict future hypoglycemia (for example, within the next 30 minutes) and pre-emptively suspend insulin delivery before hypoglycemia occurs." (PMID 35733769, 2022). "Metformin does not cause hypoglycemia because it does not increase insulin secretion, which renders it a more favorable option than other oral antidiabetic medications." (PMID 35625692, 2022). "Hypoglycemia is a rare complication of AN as glucose homeostasis is maintained by compensatory phenomena including increased secretion of GH and cortisol as well as decreased gluconeogenesis due to reduced insulin." (PMID 35011105, 2022). "Chronic high-dose OPFR exposure caused fasting hypoglycemia in male rats without altering glucose tolerance or insulin sensitivity; unfortunately, this study did not assess plasma insulin levels." (PMID 35156417, 2022). "In this study, they divided the patients into two groups: those who received a GFD from those on a regular diet for a year and studied the frequency of hypoglycemia and the effects on height, weight, HbA1c, insulin dose requirement, and bone mineral homeostasis as outcomes." (PMID 35399440, 2022). "Additionally, patients initiated with a short acting insulin regimen as a component of premixed insulin need to be highly vigilant to recognize the symptoms of hypoglycemia, and self-management to the monitoring of blood glucose levels." (PMID 36149907, 2022). "In our study, combination treatment of dapagliflozin and insulin did not raise the risk of hypoglycemia, and the same outcome was also obtained for severe hypoglycemia." (PMID 35872994, 2022). "Indeed, impaired epinephrine secretion in response to insulin-induced hypoglycaemia has reported in patients with SAI33,34." (PMID 35042934, 2022). "This delayed hypoglycaemia is secondary to the disruption of gluconeogenesis by alcohol, which, followed by a depletion of available glycogen stores overnight, and in the presence of exogenous insulin, precipitates hypoglycaemia." (PMID 34277981, 2021).
Hypoglycemia (continued). "However, numerous barriers hinder the achievement of this goal, first of all the frequent episodes of hypoglycemia typical in patients treated with insulin as T1D patients, or sulphonylureas as T2D patients." (PMID 34638984, 2021). "This increases the timeliness of insulin dose adjustment and hypoglycemia correction." (PMID 33836817, 2021). "In a national study examining insulin-related hypoglycemia and errors leading to ED visits, precipitating factors for insulin-related hypoglycemia were documented in only 20.8% of cases, indicating that the majority of precipitating factors are still left to be identified." (PMID 34001014, 2021). "While cccp‐1 knockout in C. elegans results in a neurologic phenotype of impaired and slowed locomotion, homozygous Otg1/CCDC186 knockout mice show severe postnatal growth retardation and preweaning lethality as well as impaired glucose metabolism with hypoglycemia and low levels of serum insulin." (PMID 33259146, 2021). "Adverse reactions to insulin, such as hypoglycemia, played a smaller role." (PMID 33402226, 2021). "Due to our study design, we were unable to confirm that the hypoglycemia rates were higher with treatment received prior to insulin analogues, as hypothesized." (PMID 33905628, 2021). "Adult data demonstrates better glucose control with less hypoglycemia on basal-bolus regimens using the previously discussed rapid-acting analogs with newer long-acting insulin analogs compared to NPH insulin/regular human insulin." (PMID 37745178, 2021). "Since the study assesses hypoglycemia after insulin injection, this prevalence may be due to the poor practice of insulin injection." (PMID 34690922, 2021). "Sodium glucose co-transporter-2 inhibitors (SGLT 2 inhibitors) are newer anti-hyperglycemic agents, which improve glycemic control independent of insulin secretion with a low risk of hypoglycemia." (PMID 33437256, 2021). "In a meta-analysis, SGLT2is ameliorated glycemic efficacy outcomes accompanied by a lower insulin dose requirement without increasing the risk of hypoglycemia." (PMID 33651228, 2021). "However, a better recovery from hypoglycemia with IV aspart was seen when compared to RHI as depicted by lesser time to withhold insulin infusion after a hypoglycemia episode." (PMID 34071359, 2021). "Furthermore, among 668 participants administered with once-daily IDegAsp in four studies and 677 participants administered with once-daily basal insulin, 77 (11.5%) and 129 (19.1%) demonstrated at least one nocturnal confirmed hypoglycemia event, respectively." (PMID 34564455, 2021). "This could be explained by the good knowledge of insulin self-administration, which may prevent related hypoglycemia due to an inappropriately high dose of insulin." (PMID 34690922, 2021). "At least one overall confirmed case of hypoglycemia was reported in 728 of 1129 (64.5%) participants who were administered with twice-daily IDegAsp in six RCTs, and 541 of 1269 (67.6%) participants who were administered with conventional premixed insulin." (PMID 34564455, 2021). "For those treated with insulin, the specific negative impacts were associated with hypoglycemia and their ability to take part in and enjoy social life." (PMID 34507618, 2021). "A gene response to insulin-induced hypoglycemia was estimated in the mouse retina by an array." (PMID 34360550, 2021). "While 209 (8.8%) patients with oral drugs + insulin treatment also had hypoglycaemic glucose values (n = 1405 (5.7%)), only a small number of patients had nocturnal hypoglycaemia treated either with diet only or oral drugs, similar to patients treated with non-insulin injectables." (PMID 33672913, 2021). "However, overdosing of insulin can provoke too low BG concentration (hypoglycemia), with severe consequences if untreated, including comma and death." (PMID 34064325, 2021).